FSCN1 (fascin actin-bundling protein 1)
Diseases named in the same sentence as FSCN1 in open-access papers (continued):
Sharing a sentence is not in itself a finding about the gene and the disease.
tumor (continued). "We also dissected the tumor suppressor roles of miR-133b in GC cells and found that it was partially through targeting oncogenic FSCN1." (PMID 25433493, 2014). "Functionally, miR-133a can suppress tumor cell invasion and migration and targeted the expression of FSCN1." (PMID 22292984, 2012). "Regarding miR-133a in human cancers, our previous studies demonstrated that miR-133a functions as a tumor suppressor and targets multiple oncogenes, such as FSCN1, LASP1, CAV1 and GSTP1." (PMID 21378409, 2011). "Over-expression of FSCN1 in a variety of tumours such as lung, prostate, oesophageal, breast, colon, pancreas, ovary, and skin cancers usually correlates with high-grade, extensive invasion, distant metastasis, and poor prognosis." (PMID 20160723, 2010). "Our immnohistochemical study consistently showed that the expression levels of FSCN1 were correlated with advanced tumour stage." (PMID 20160723, 2010). "In situ hybridisation revealed that miR-145 expression was markedly repressed in the tumour lesion in which FSCN1 was strongly stained." (PMID 20160723, 2010). "Furthermore, Fascin-1 levels in HCC samples and paired tissues were analyzed using The Cancer Genome Atlas (TCGA) database, revealing a marked increase in FSCN1 levels in 50 paired tumor samples." (PMID 40093808, 2025). "Analysis of the Pan-Cancer dataset integrating International Cancer Genome Consortium (ICGC) and The Cancer Genome Atlas (TCGA) further revealed a significant correlation between FRA1 levels and AXL, CDK6, and FSCN1 expression in 1210 tumor samples of all cancer types." (PMID 41286309, 2025). "Additionally, we found that FSCN1 expression was higher in tumor tissue cells than in cells of the tumor microenvironment, and the relative number of circulating FSCN1+ tumor cells was approximately threefold higher than the number of FSCN1+ leukocytes." (PMID 40669873, 2025). "Notably, we found that the level of FSCN1+ tumor cells in tissue was 6.45-fold higher in HNSCC patients with relapses within one year after anticancer treatment compared with HNSCC patients without disease progression (P ˂ 0.05)." (PMID 40669873, 2025). "However, there are "gaps" in understanding the role of FSCN1 in tumor progression, including in HNSCC." (PMID 40669873, 2025). "Moreover, FSCN1 is highly expressed in several types of tumors and plays roles in biological processes like tumor cell migration, invasion, and metastasis." (PMID 37597213, 2024). "Interestingly, CC genotype of FSCN1 rs1640233 was more likely to progress tumor size and lymph node invasion in BC cases (p-value = 0.04 and 0.02, respectively)." (PMID 38587571, 2024). "In BC, FSCN1 is crucial for predicting aggressive tumor behavior, especially in advanced stages." (PMID 38587571, 2024). "Moreover, an in vivo PCa mouse xenograft study found that inhibition of FSCN1 effectively blocked tumor progression." (PMID 37634036, 2024). "In ACC, studies have indicated that elevated levels of FSCN-1 in the bloodstream could reflect tumor activity and burden." (PMID 39682247, 2024). "Ifitm6+, Hcar2+, Retnla+, Spp1+, C1qb+, and Fscn1+ macrophages mainly existed in tumor tissues." (PMID 36718369, 2023). "Using RNA-seq technology, we demonstrated that FSCN1 regulates AS, which may regulate tumor proliferation by promoting the expression of cell-cycle-related genes." (PMID 38077434, 2023). "By effectively blocking F-actin cross-linking activity of FSCN1, NP-G2-044 has demonstrated anti-tumor metastasis effects in preclinical studies and in a phase Ia clinical trial for patients with metastatic or advanced refractory solid tumor malignancies (Clinicaltrials.gov NCT03199586)." (PMID 37596693, 2023). "Therefore, we conclude that FSCN1 regulates the expression of genes related to the tumor malignant phenotype in A549 cells, indicating a potential regulatory mechanism." (PMID 38077434, 2023). "We next assessed the functional impact of FSCN1 knockdown on tumour growth in vivo." (PMID 37875732, 2023).
tumor (continued). "Interestingly, the pharmacological inhibition of Fscn1 activity in tumor-bearing mice has been reported to promote anti-tumor activity also due to direct effects on intratumoral DCs." (PMID 38069260, 2023). "Taken together, these in vitro and in vivo studies suggest that FSCN1 knockdown could inhibit the proliferation and migration of neuroendocrine-like cells, leading to tumour growth delay." (PMID 37875732, 2023). "The results of this study confirmed that miR-585-3p could negatively regulate the expression of FSCN1 and inhibit the proliferation, migration, and invasion of OC tumor cells." (PMID 35602576, 2022). "Altogether, our results suggest that in vivo treatment with Fscn1 inhibitors for tumor therapy could affect the DC immunophenotype and DC/T-cell interactions." (PMID 35681718, 2022). "Moreover, further significantly upregulated genes such as DOCK10, GPC6, and FSCN1 have been related to enhanced tumor cell migration and/or invasion." (PMID 35163822, 2022). "Our results suggest that systemic application of Fscn1 inhibitors for tumor therapy may also modulate antitumor immune responses." (PMID 35681718, 2022). "In addition, as a new type of angiogenic factor, FSCN1 has been proved to play an important role in tumor growth and development and is a new target of antiangiogenesis therapy." (PMID 35602576, 2022). "As reported, FSCN1 is highly expressed in many types of tumor tissue." (PMID 35178306, 2022). "Altogether, our results confirm the necessity of performing comparative, in-depth in vivo studies employing distinct Fscn1 inhibitors and subsequent ex vivo analysis to delineate, in detail, by which mechanisms these may inhibit tumor growth." (PMID 35681718, 2022). "Altogether, our results indicate that Fscn1 inhibitors developed for tumor therapy may also interfere with adaptive antitumor immune responses on several levels." (PMID 35681718, 2022). "In addition, FSCN1 regulates tumor cell migration, invasion and metastasis by participating in key oncogenic pathways such as EMT, PI3K/AKT, Wnt/β-catenin, and MAPK." (PMID 36275729, 2022). "Consistently, FSCN1 knockdown promoted cell apoptosis in tumor cells with PIK3CA alterations." (PMID 34249689, 2021). "FSCN1 is an actin-binding protein that has been reported to have pro-tumor functions." (PMID 34249689, 2021). "This is the first study also assessing serum levels of FSCN1 after the removal of the tumor mass." (PMID 34248854, 2021). "Notably, FSCN1 is upregulated by TGFβ/Nodal signaling also in a range of tumor cells and overexpressed in different carcinomas where correlates with the clinical aggressiveness, suggesting that FSCN1 sustains TGFβ signaling also during tumor progression." (PMID 33672325, 2021). "Therefore, FSCN1 is a potential biomarker for aggressive, metastatic cancers and is a therapeutic target for blocking tumor cell migration, invasion, and metastasis." (PMID 33614909, 2021). "Furthermore, FSCN1 is also highly expressed in many types of tumors (reviewed in Machesky and Li11) and promotes tumor cell migration, invasion, and metastasis." (PMID 33614909, 2021). "Likewise, small molecule inhibitors can reduce tumor cell migration and invasion and help pave the way against FSCN1-induced tumors." (PMID 34830909, 2021). "Consequently, contradictory evidence is reported in the literature regarding tumor expression of FSCN1, prompting a more detailed analysis." (PMID 34737886, 2021). "This leads us to propose a hypothesis that FSCN1 may have a pro-tumor function among patients with PIK3CA alterations." (PMID 34249689, 2021). "As expected, FSCN1 protein level was higher in tumor tissues than in adjacent tissues." (PMID 34016787, 2021). "This suggested that PIK3CA-altered tumor cells may specifically rely on FSCN1 to survive radiotherapy treatment." (PMID 34249689, 2021).
tumor (continued). "Circulating FSCN1 may be somehow involved in tumor progression, namely in the metastatic process, as well as in tumor relapse, supported by the evidence that FSCN1 in pre-surgery samples is predictive of DFS but not of the OS." (PMID 34248854, 2021). "Moreover, FSCN1 is related to apoptosis-associated genes, and its expression level is positively associated with YWHAZ specifically in tumor tissues and cells with PIK3CA alterations." (PMID 34249689, 2021). "In addition, injection of cancer cells, stably knocked down FSCN1 in nude mice, showed a suppressed tumor growth rate compared to control cells." (PMID 33614909, 2021). "There is previous evidence in the literature of FSCN1 involvement in tumor metabolism." (PMID 35069968, 2021). "Small molecule inhibitors of FSCN1 can block tumor cell migration, invasion, and metastasis." (PMID 33614909, 2021). "FSCN1 expression was found to be positively correlated with ACC tumour purity (r = 0.349, p = 2.33e− 03), and negatively correlated with the infiltration signature of CD8+ T cells (r = − 0.372, p = 1.19e – 03), while FOXM1 showed a weak correlation with B cell and dendritic cell signatures." (PMID 31783819, 2019). "We then verify our hypothesis by studying TSCC cell viability and trans-migration in vitro, tumor growth in vivo and FSCN1 expression and patient survival analysis." (PMID 31043585, 2019). "With in vitro and in vivo experiments, we found that FSCN1 might be an important gene in promoting tumor growth and metastasis." (PMID 31043585, 2019). "The majority of proteins (ACTR2, CSTB, LTA4H, PGK1, NDRG1, FSCN1, ITGAV, THBS2) significantly associated with clinical parameters showed lower expression in the ITF of the tumor stroma or neoplastic islands, with the exception of COL6A1, COL1A2, S100A8, S110A9, and MB." (PMID 30185791, 2018). "There is evidence that miR-145 could inhibit tumor cell proliferation, invasion and metastasis by targeting FSCN1." (PMID 28388536, 2017). "Our findings indicate that fscn1a and Nodal signalling promote endoderm formation through a positive-feedback loop and may allow for a better understanding of how TGF-β signalling is elevated in Fscn1 overexpressed metastatic tumours." (PMID 27545838, 2016). "miR-145, miR-133a and miR-133b were also revealed to have tumour suppressive effects inhibiting ESCC cell proliferation and invasion via repression of the FSCN1 gene, whereas FSCN1 was known to be involved in the metastasis of multiple tumour types and regulated by a number of miRNAs." (PMID 23478435, 2013). "In summary, through our microRNA profiling in BC, we have found that FSCN1 might have an oncogenic function in BC and miR-145 and miR-133a might function as tumour suppressors through direct repression of FSCN1 in BC." (PMID 20160723, 2010). "Tumour suppressive miR-145 and miR-133a directly control oncogenic FSCN1 in BC." (PMID 20160723, 2010). "Interestingly, this DC subset not only expressed activation markers, but they also had an Il2b signature and expressed migratory markers, including Fscn1 and Ccr7 which are important in facilitating DC migration to tumor-draining lymph nodes to shuttle between lymph nodes and the CNS." (PMID 40842154, 2025). "Therefore, Fscn1 inhibitors have been developed and clinically tested for tumor therapy." (PMID 38069260, 2023). "Moreover, pFscnLuc mediated high reporter gene expression in Fscn1-expressing tumor cells." (PMID 38069260, 2023). "In addition, FSCN1 silencing further impairs in vivo tumour growth." (PMID 37875732, 2023). "In addition, immortalized tumor cell lines were reported to express Fscn1 and have frequently been used to as cell models to delineate the interaction of Fscn1 with other cytoskeletal proteins, such as cofilin-1 and Daam1 (disheveled-associated activator of morphogenesis 1), among others." (PMID 35681718, 2022).
tumor (continued). "In light of the important role of TAMs in conferring tumor progression, e.g., by neoangiogenesis, and in the release of anti-inflammatory mediators, such as IL-10, to promote tumor immune evasion, it is possible that inhibition of Fscn1 in TAMs may contribute to inhibition of tumor growth." (PMID 35681718, 2022). "Increasing evidences suggested that elevated level of FSCN1 was significantly correlated with increased metastatic potential and more aggressive phenotypes in a variety of tumors 26-29, and inhibiting FSCN1 could block the migration and metastasis of tumor cells." (PMID 33753991, 2021). "In addition, FSCN1 can act as a mediator of self‐seeding of metastatic circulating tumor cells (CTCs); FSCN1 can also mediate the invasiveness of tumor cells in vitro and metastasis in vivo, regroup the primary tumor, and assist in the completion of “self-seeding”." (PMID 34249689, 2021). "We therefore hypothesize that FSCN1 is a downstream effector protein that is upregulated to promote migration and invasion by remodeling cytoskeletal organization in response to various oncogenic signals in tumor cells." (PMID 33614909, 2021). "Moreover, it was recently demonstrated that targeted inhibition of FSCN1 could interfere with tumor invasion and metastatic potential." (PMID 34737886, 2021). "However, it was still unknown whether miR-133b played its tumor suppressor roles through targeting FSCN1 in GC." (PMID 25433493, 2014). "In addition, they also found that miR-133b could affect the biological behavior of the tumor through regulating gene expression of FSCN1." (PMID 25414595, 2014). "They identified FSCN1 as a positive regulator of the angiogenic factor ANGPTL4, linking it to tumor angiogenesis." (PMID 41148856, 2025). "The results showed that in tumor tissues of HNSCC patients, the FSCN1 levels were significantly higher in tumor cells and B-lymphocytes than in macrophages and fibroblasts." (PMID 40669873, 2025). "Fascin actin-bundling protein 1 (FSCN1) and protein tyrosine phosphatase receptor type F (PTPRF) promote tumor progression in LUSC." (PMID 38841622, 2024). "Predictably, images of the liver and H.E. staining showed that overexpression of SIAH1 inhibited tumor growth and intrahepatic metastasis, and immunohistochemistry was used to analyze the expression of SIAH1, ADRM1, UCHL5, FASN, and FSCN1." (PMID 39075049, 2024). "The expression levels of GAPDH, FSCN1, SLC2A1, FAM83A, PLEK2, and GJB3 all presented significant differences between tumor tissues and normal tissues." (PMID 38370379, 2024). "In BCa, IGF2BP1 promotes tumour proliferation, migration and invasion by regulating the expression of MYC and FSCN1." (PMID 36747239, 2023). "Here, we investigated the novel RNA-binding function of FSCN1 and found that FSCN1 inhibits protein tyrosine kinase 6 (PTK6) expression by binding to its pre-mRNA, thus facilitating tumor progression in ESCC." (PMID 35401239, 2022). "We found that the RNA expression levels of PDLIM3, PAM, PDLIM7, FSCN1 and LGALS3 were significantly upregulated in tumor samples, which provides ideas for further studies." (PMID 36177006, 2022). "PTK6-T2 blocked the binding between FSCN1 and the pre-mRNA of PTK6, and thus reversed the promotion effect of FSCN1 on ESCC tumor progression via the AKT/GSK3β signaling pathway." (PMID 35401239, 2022). "documented that FSCN1 knockdown suppresses NSCLC (A549 cells) proliferation and tumor growth through the MAPK signaling pathway." (PMID 33614909, 2021). "ADORA2A-AS1 exerts tumor-suppressive roles in HCC via competitively binding HuR, decreasing the binding of HuR to FSCN1 transcript, downregulating FSCN1 transcript stability, repressing FSCN1 expression, and repressing AKT pathway." (PMID 34733789, 2021). "MiR-133a plays the tumor suppressive role via tageting and regulating the genes like SOX4, EGFR, FSCN1, COL1A1 and so on." (PMID 33391416, 2021).
tumor (continued). "Meanwhile, miR‐185‐3p and miR‐632 expression levels were lower in CRC tissues compared with that in the matched para‐tumor tissues, and negatively correlated with LINC00152 and FSCN1 levels." (PMID 32042551, 2020). "So we compared FSCN1 expression between TSCC and normal cell lines and knocked down FSCN1 in TSCC cells to observe its influence on the viability and trans-migration in vitro and tumor growth in vivo." (PMID 31043585, 2019). "Knockdown of FSCN1 reduced TSCC cell viability and trans-migration in vitro and impaired tumor growth in vivo." (PMID 31043585, 2019). "Our research aims to identify the role of the epithelial-mesenchymal transition (EMT) related genes FSCN1 and FOXM1 in the tumour microenvironment and assess their prognostic value in ACCs." (PMID 31783819, 2019). "FSCN1 and MMP14 are proteins that facilitate tumor progression and formation of a suitable tumor microenvironment." (PMID 30046565, 2018). "Overall, miR-24 acts as a novel tumor suppressor in the development and progression of NPC through targeting FSCN1, which providing new insight into the mechanisms of NPC carcinogenesis and suggesting the possibility of miR-24 as a therapeutic target." (PMID 26503504, 2015). "Taken together, our results suggest that miR-24 functions as a tumor suppressor by inhibiting NPC cell proliferation and invasion through targeting the oncogene of FSCN1 and contribute to the development and progression of NPC." (PMID 26503504, 2015). "Mechanistically, the effects of miR-191 and miR-425 on tumor growth and invasion require, at least in part, the suppression of SATB1, CCND2 and FSCN1." (PMID 23505378, 2013). "Importantly, combining the FSCN1 inhibitor NP-G2-044, with TMZ therapy resulted in stronger anti-tumor effects both in vitro and in vivo." (PMID 41454694, 2025). "In patients with disease progression, the proportion of FSCN1+ tumor cells was six-fold higher than in patients without progression (Р ˂ 0.05)." (PMID 40669873, 2025). "While FSCN1 has been extensively reported in the context of tumor development, no studies have yet detailed its specific role or mechanism in T2DM." (PMID 37597213, 2024). "The mechanism whereby FSCN1 influences tumor migration and invasion is well understood, whereas the mechanism whereby FSCN1 promotes tumor cell proliferation and growth is not." (PMID 38077434, 2023). "We used qRT‒PCR to detect the expression of FSCN1 in 40 paired OSCC tumor tissues (tumor) and neighboring noncancerous tissues." (PMID 37491232, 2023). "Considering this information, we propose the hypothesis that the downregulation of circFAM13B in MB may upregulate IGF2BP1 expression levels and, thus, promote tumor growth through deregulation of the MYC and FSCN1 oncogenes." (PMID 37835380, 2023). "Growing evidence has shown that miR-133a is downregulated and plays tumor suppressor roles in cancer and that it can inhibit proliferation, migration, and invasion of HCC cells by targeting several genes such as IGF-1R, FSCN1, and FOSL2 through the TGF-β/Smad3 signaling pathway." (PMID 35432524, 2022). "First, we determined the effects of the two structurally distinct Fscn1 inhibitors, NP-G2-044 and BDP-13176, on primary splenic DC when applied at a range of concentrations previously reported to confer Fscn1 inhibition in tumor cells (10−6–5 × 10−5 M)." (PMID 35681718, 2022). "Third, previous studies have shown that FSCN1 is highly expressed in many different cancer types; therefore, it is not specific to any tumor tissue type to be a good biomarker." (PMID 33614909, 2021). "This suggests that FSCN1 may play a key role in PIK3CA-altered tumor cells and that the survival of PIK3CA-altered tumor cells under radiotherapy treatment may be specifically accompanied by high expression of the FSCN1 gene." (PMID 34249689, 2021). "ADORA2A-AS1 exerts tumor-suppressive roles in HCC via binding HuR and repressing FSCN1/AKT axis." (PMID 34733789, 2021).